RNY1P11 (RNY1 pseudogene 11)
Gene: Miscellaneous RNA gene on chromosome 7 (129,164,849 to 129,164,961, forward strand). Ensembl gene ENSG00000200629.
Homologues: Orthologues: chimpanzee Y_RNA (100% identical), guinea pig Y_RNA (90% identical), guinea pig Y_RNA (88% identical). Paralogues in human: RNY1 (91% identical), Y_RNA (91% identical), Y_RNA (88% identical), RNY1P10 (87% identical), Y_RNA (87% identical), Y_RNA (86% identical), RNY1P8 (85% identical), Y_RNA (85% identical), Y_RNA (84% identical), RNY1P12 (83% identical), Y_RNA (83% identical), RNY1P15 (82% identical), and 96 more.